ABCG2 (ATP binding cassette subfamily G member 2 (JR blood group))
Diseases named in the same sentence as ABCG2 in open-access papers (continued):
Sharing a sentence is not in itself a finding about the gene and the disease.
invasive carcinoma (1 paper, 2022). A carcinoma that is not confined to the epithelium, and has spread to the surrounding stroma. "Specifically, the co-localization of p75ICD and the marker ABCG2 was observed in invasive carcinoma CSCs, where ABCG2 staining was perinuclear within cells as well as pericellular (asterisks), as expected based on the ABCG2 expression in extracellular vesicles in squamous cancer." (PMID 35681602, 2022).
ischemic cardiomyopathy (1 paper, 2023). Ischemic cardiomyopathy is a cardiomyopathy in which a weakness in the muscle of the heart due to inadequate oxygen delivery to the myocardium with coronary artery disease being the most common cause. "The levels of ABCG2 mRNA in cardiomyopathic hearts (both dilative and ischemic cardiomyopathy) were higher than in non-failing hearts." (PMID 38139840, 2023).
large cell lung cancer (1 paper, 2017). "H460/MX20 are derived from large cell lung cancer H460 cell line and then transformed into ABCG2-overexpressing cells by mitoxantrone’s induction, which are widely used in study of multidrug resistance (MDR) in vitro." (PMID 28059154, 2017).
leukopenia (1 paper, 2018). "In this study polymorphic variants in genes encoding membrane transporters, both influx (SLC22A16) and efflux ones (ABCB1, ABCG2, ABCC2), were the independent predictors of all studied symptoms of FAC myelotoxicity, excluding overall leukopenia." (PMID 29507678, 2018).
liver fibrosis (1 paper, 2025). "We found that genetic variants in ABCG2, which mediate elevated SUA levels, have significant causal effects on the development of HCC, CCA, and liver fibrosis." (PMID 40282409, 2025).
lung squamous cell carcinoma (1 paper, 2024). "This suggests that unmethylated ABCG2 takes part in lung squamous cell carcinoma progression." (PMID 39457707, 2024).
Lymphatic Metastasis (1 paper, 2012). Transfer of a neoplasm from its primary site to lymph nodes or to distant parts of the body by way of the lymphatic system. "The difference in expression of ABCG2 when contrasted with V-ATPase expression in the lymphatic metastasis group and non-lymphatic metastasis group were statistically significant (P < 0.0001)." (PMID 23244569, 2012).
mucinous adenocarcinoma (1 paper, 2023). An invasive adenocarcinoma composed of malignant glandular cells which contain intracytoplasmic mucin. "With regard to histological subtypes, the highest frequencies of ABCG2 changes were noted in mucinous adenocarcinoma of the colon and rectum." (PMID 37445716, 2023).
mucositis (1 paper, 2023). Mucositis is inflammation and damage of the mucous membranes lining the mouth and other parts of the gastrointestinal (GI) tract. "The ABCG2 rs2231142 statistically correlated with a higher extent of mucositis and xerostomia (CC genotype)." (PMID 36982571, 2023). "The ABCG2 gene was significantly correlated with the duration of grade maximum for mucositis and xerostomia." (PMID 36982571, 2023).
myelodysplastic syndrome (1 paper, 2024). A clonal hematopoietic disorder characterized by dysplasia and ineffective hematopoiesis in one or more of the hematopoietic cell lines. "Last, overexpression of Abcg2 in mice has been shown to drive myelodysplastic syndrome, and Abcg2 expression is particularly high in patients with myelodysplastic syndrome." (PMID 38277455, 2024).
Myocardial fibrosis (1 paper, 2017). "This suggests that hypoxia per se and not hypoxia-induced changes in afterload were the main cause for elevated ventricular end-diastolic pressure and myocardial fibrosis in ABCG2 KO animals." (PMID 28270772, 2017). "Our study shows that the hypoxia-induced structural changes in the ventricular myocardium are markedly exaggerated in ABCG2 KO mice, suggesting that ABCG2 protects from hypoxia-induced myocardial fibrosis." (PMID 28270772, 2017).
narcolepsy (1 paper, 2022). A sleep disorder characterized by a tendency for excessive sleepiness during the day which occurs even after adequate sleep in the nighttime. "For tea consumption, ABCG2 was detected, which was associated with narcolepsy, a disorder related to changes in brain function." (PMID 35631318, 2022).
non-Hodgkin lymphoma (1 paper, 2014). Distinct from Hodgkin lymphoma both morphologically and biologically, non-Hodgkin lymphoma (NHL) is characterized by the absence of Reed-Sternberg cells, can occur at any age, and usually presents as a localized or generalized lymphadenopathy associated with fever and weight loss. "They found that elevated expression of ABCG2 was signature for the patients that didn’t respond to chemotherapy and for cases with shorter progression-free survival time in a 2.5 years follow-up and concluded that ABCG2 may be a crucial factor in primary resistance of non-Hodgkin’s lymphomas." (PMID 25268163, 2014).
photosensitivity (1 paper, 2021). "Nevertheless, our data suggest that ABCG2 dysfunction may be an overlooked etiology of “photosensitivity of unknown cause” and that it might also affect the severity of phototoxic photosensitivity." (PMID 34009629, 2021). "We also speculate that an ordinary diet can influence the clinical symptoms of photosensitivity in individuals harboring dysfunctional ABCG2 alleles." (PMID 34009629, 2021). "In the 23 patients with photosensitivity that lacked apparent causes, lower ABCG2 function was significantly correlated with higher erythrocyte protoporphyrin levels (P = 0.012), suggesting that ABCG2 dysfunction can lead to the accumulation of protoporphyrin in humans." (PMID 34009629, 2021).
polycystic kidney disease (1 paper, 2014). A usually autosomal dominant and less frequently autosomal recessive genetic disorder characterized by the presence of numerous cysts in the kidneys leading to end-stage renal failure. "In fact, a suggestive local interaction pair of rs2725227 and rs2725222 (distance = 14 kb, Pint was 1.2E−05 in ARIC and 9.6E−03 in FHS) was near ABCG2, with both SNPs were located in PKD2, a candidate causal locus of polycystic kidney disease and regulator of SUA levels." (PMID 24821702, 2014).
porphyria (1 paper, 2016). Porphyria is a group of diseases in which substances called porphyrins build up, negatively affecting the skin or nervous system. "Although elevated porphyrins are a hallmark of multiple types of porphyria, the role of porphyrin transporters (TSPO, ABCG2, ABCB6 and FLVCR1) as modulators of disease severity has not been investigated." (PMID 27507172, 2016).
primary progressive MS (1 paper, 2020). "In retrospective analyses, association of SNPs in ABCB1 and ABCG2 genes with drug effects has been shown at least for relapsing and secondary progressive MS but not for primary progressive MS." (PMID 31915017, 2020).
psoriatic arthritis (1 paper, 2023). Joint inflammation associated with psoriasis. "Specifically, following the multivariate analysis, the ABCG2 rs13120400-T allele was found to be associated with the risk of grade 1–4 toxicity, adjusted for the development of psoriatic arthritis." (PMID 37761008, 2023).
pulmonary hypertension (1 paper, 2017). Increased pressure within the pulmonary circulation due to lung or heart disorder. "We provide evidence that loss of ABCG2 under hypoxia leads to biventricular fibrosis and diastolic dysfunction, but does not affect the development of pulmonary hypertension." (PMID 28270772, 2017). "ABCG2 deficiency did not influence hypoxia-induced pulmonary hypertension or vascular remodeling." (PMID 28270772, 2017). "This notion is also supported by an increased ABCG2 expression in the RV of pulmonary arterial banded (PAB) mice, an animal model recapitulating solely RV pressure overload observed in pulmonary hypertension." (PMID 28270772, 2017).
rectum (1 paper, 2023). "Using publicly available data, ABCG2 was shown to be underexpressed in colon and rectum adenocarcinomas, with lower expression compared to both the adjacent nonmalignant lung tissues and non-tumour lung tissues of healthy individuals." (PMID 37445716, 2023).
resistant cancer (1 paper, 2021). "In taxane-resistant cancer, ABCB1 (encoding multidrug resistance protein 1; MDR1 or P-glycoprotein) and ABCG2 (encoding breast cancer resistance protein; BCRP) ABC transporters have been studied well as transporters of paclitaxel in several carcinomas." (PMID 34503223, 2021).
seborrheic keratosis (1 paper, 2021). A common benign skin neoplasm usually affecting older individuals. "Stronger staining intensities with anti-ABCG2 and anti-uric acid antibodies in lesional skin of seborrheic keratosis with GDA upregulation supported an association between ABCG2 and uric acid in seborrheic keratosis." (PMID 34830382, 2021). "Stronger staining intensities with anti-PDZK1 and anti-ABCG2 antibodies in lesional epidermis of seborrheic keratosis also supported clinical implications of their relations." (PMID 34830382, 2021). "Immunofluorescence study for skin specimens of patients with seborrheic keratosis with stronger GDA staining intensities using anti-ABCG2 and anti-uric acid antibodies showed stronger staining intensities in lesional epidermis." (PMID 34830382, 2021). "Staining intensity with an anti-ABCG2 antibody was stronger in lesional epidermis compared to normal epidermis of seborrheic keratosis showing increased PDZK1 staining intensity." (PMID 34830382, 2021).
sitosterolemia (1 paper, 2021). A rare autosomal recessive sterol storage disease characterized by the accumulation of phytosterols in the blood and tissues. "Other mutations to these positions are found as variants in vivo, some causing sitosterolemia, such as mutations to E146 in ABCG5, analogous to E138 in ABCG2." (PMID 33809494, 2021).
Sjögren syndrome (1 paper, 2011). "Whereas acinar unit was decreased in the Sjögren syndrome group, and acinar unit with ABCG2 expression was also decreased." (PMID 21655359, 2011). "ABCG2 was expressed in intercellular junction and cytoplasm of most acinar unit regularly in the non-Sjögren syndrome group." (PMID 21655359, 2011). "ABCG2 was expressed in acinar cells in both sjogren and non-Sjogren syndrome." (PMID 21655359, 2011). "Progenitor cell marker expression (p63, nucleostemin, and ABCG2) was weaker in the Sjögren syndrome group than in non-Sjögren syndrome group." (PMID 21655359, 2011).
skin reaction (1 paper, 2024). "The presence of adverse reactions, such as skin reactions or diarrhea, can be explained by the roles of transporters in the oral absorption and elimination pathways of gefitinib, as ABCG2 is highly expressed in the intestine and liver." (PMID 39204145, 2024).
spontaneous abortion (1 paper, 2019). Expulsion of the product of FERTILIZATION before completing the term of GESTATION and without deliberate interference. "Likewise, preDSC lines expressed the multipotentiality markers OCT-4, NANOG, and ABCG2, their clonogenic efficiency ranged between 4 and 15%, they remained alive for weeks in xenogeneic transplants, and they had a therapeutic effect in an immune-based murine model of spontaneous abortion." (PMID 31200769, 2019).
synovial sarcoma (1 paper, 2022). "In synovial sarcomas we demonstrated positive correlation of ABCC1 expression with SI (Ifo) and SI (Dox + Ifo) as well as ABCG2 expression gene with SI (Doс)." (PMID 35328603, 2022).
teratocarcinoma (1 paper, 2012). A germ cell tumor characterized by the presence of an embryonal carcinoma component and a teratoma component. "Although we found that the ABCG2+hox cells were highly teratomagenic, ABCG2+hox cells did not exhibit teratocarcinoma activity, suggesting that the enhanced stemness state did not lead to malignant transformation." (PMID 22689594, 2012). "Taken together, we concluded that the ABCG2+hox fraction underwent a temporary but measurable phenotypic switch to an enhanced stemness state of extreme self-sufficiency but did not exhibit malignant transformation to teratocarcinoma." (PMID 22689594, 2012).
teratoma (1 paper, 2012). A non-seminomatous germ cell tumor characterized by the presence of various tissues which correspond to the different germinal layers (endoderm, mesoderm, and ectoderm). "The ABCG2+hox and ABCG2+nox were injected subcutaneously into immunocompromised mice to obtain teratomas, and a serial dilution assay was performed to compare the teratomagenic frequency between the ABCG2+hox and ABCG2+nox." (PMID 22689594, 2012).
testicular germ cell tumor (1 paper, 2022). A germ cell tumor arising from the testis. "For the pathological stage, significant correlations emerge among KICH, KIRC, testicular germ cell tumors (TGCT), and THCA, of which KIRC, THCA, and KICH show ascending tendency with increasing expression of ABCG2, and TGCT shows the opposite trend." (PMID 36555598, 2022).
ulcer disease (1 paper, 2022). A lesion on the surface of the skin or a mucous surface, produced by the sloughing of inflammatory necrotic tissue. "Considering this and previous findings, the decreased expression of ABCG2 in the model of ulcer disease caused by NaT damage remains unanswered." (PMID 35056399, 2022). "It was reported that the more intense the infection of ulcer disease, the higher the level of ABCG2 expression." (PMID 35056399, 2022).
cancer (1,428 papers, 1996 to 2026). A tumor composed of atypical neoplastic, often pleomorphic cells that invade other tissues. "The multidrug resistance-associated protein-1 (MRP1 or ABCC1), and breast cancer resistance proteins (BRCP or ABCG2) are crucial MDR-associated ABC transporters." (PMID 40260304, 2025). "Previously, reversal mutation of BRCA2, loss of PARP1 protein expression, and overexpression of drug efflux pumps ABCB1 (p‐glycoprotein) and ABCG2 (BCRP) have been linked to acquired resistance to PAPRi in BRCA2 mutant cancer." (PMID 40874518, 2025). "The major three ABC transporter genes implicated in cancer drug resistance are ABCB1, ABCC1, and ABCG2." (PMID 40430358, 2025). "ABCB1 (P-gp/P-glycoprotein ABCB1), multidrug resistance-associated proteins (MRPs/ABCC family) and breast cancer resistance protein (BCRP/ABCG2) have been widely implicated in the development of drug resistance across various cancer types." (PMID 40867257, 2025). "Most often, ABCG2 expression in cancers has been associated with poor prognosis, although results are inconsistent, and in some an inverse association was found." (PMID 40548120, 2025). "The results revealed a 25%–30% reduction in the expression of ABCB1 and ABCG2, which encode for P-glycoprotein and breast cancer resistance protein, respectively, in NFIB-overexpressed vs. control cells (P < .05)." (PMID 40554316, 2025). "Overexpression of ABCG2 is regarded as one of the main causes of multi-drug resistance, and the ABCG2 gene expression level is increased in PDAC tissue compared to adjacent non-cancer tissue." (PMID 40272619, 2025). "One of the leading causes contributing to the reduced chemosensitivity associated with ABCG2 activity is the efflux of drugs thereby reducing their concentration within cancer cells." (PMID 38791198, 2024). "This study delved into the influence of ABCG2 on the emergence of the resistance or diminished susceptibility of cancer cells to MTX-211." (PMID 38791198, 2024). "Known for its role as a multidrug transporter, ABCG2 contributes to the pharmacokinetic properties of drugs and is implicated in the multidrug resistance phenomenon in cancer cell." (PMID 39629124, 2024). "Based on the MCP-COUNTER, XCELL, and TIDE algorithms, a significant positive correlation between ABCG2 expression and cancer-associated fibroblast infiltration was observed in LUAD, but not in LUSC." (PMID 39457707, 2024). "The high expression of ABCG2 in the cancer cells and expulsion of anticancer drugs directly cause multidrug resistance (MDR)." (PMID 38855753, 2024). "Since osimertinib had previously been identified as a substrate of both ABCB1 and ABCG2, we assessed the susceptibility of various cancer cell lines to furmonertinib." (PMID 37762275, 2023). "High Nrf2 activity in cancer cells leads to the upregulation of various proteins associated with cancer progression, including ABCG2, VEGF, HO-1, Bcl-2, p62, and MDM2." (PMID 37759607, 2023). "The inhibition of ABCG2, e.g., through a strong ABCG2-inhibitor gefitinib, restores the full susceptibility of cancer cells to photodynamic treatment." (PMID 37759900, 2023). "In the lung, AhR has been shown to induce the expression of ABCG2 and other critical genes involved in cancer stemness which has been found to be associated with an increase of stem population in osteosarcoma cells." (PMID 37696458, 2023). "Compared with the control, CRC spheroids derived from the cancer cells with TOX3 knockdown or overexpression showed decreased or elevated expression of ABCG2 and stem-like traits-associated protein markers." (PMID 37708089, 2023). "The ABCG2 from the drug-resistant cancer cells harbored a mutation at R482 (R482G/R482T) causing a gain of function." (PMID 37438132, 2023). "Dysregulated noncoding RNAs, including microRNAs (miRNAs) and long noncoding RNAs (lncRNAs), have been found to be associated with the overexpression of ABCB1, ABCG2, and ABCCs in chemoresistant cancers." (PMID 37229486, 2023).